ACAT1 (acetyl-CoA acetyltransferase 1)
Diseases named in the same sentence as ACAT1 in open-access papers (continued):
Sharing a sentence is not in itself a finding about the gene and the disease.
tumor (continued). "The gene expression of ketolytic enzymes BDH1, OXCT1 and ACAT1 were analysed in the context of MYCN amplification, INSS tumour stage progression and overall event free survival." (PMID 41420301, 2025). "Restoring ACAT1 expression increases endogenousβ-OHB levels and reverses epithelial–mesenchymal transition (EMT), indicating a potential tumor-suppressive function." (PMID 39857793, 2025). "MiR‐302a‐3p serves as a tumor suppressor for non‐small‐cell lung cancer and HCC, and its targets include ACAT1 and PRKACB." (PMID 40761482, 2025). "Phosphorylation at the Y381 site of PDP1 changes ACAT1 and PDP1 expression, regulates PDP1’s lysine acetylation, and impacts tumor cell metabolism and proliferation." (PMID 40746885, 2025). "We demonstrated that TRIM8 stabilizes PGK1 through K63 ubiquitination and recruits ACAT1, driving PGK1 acetylation, thereby enhancing PGK1-mediated glycolysis and ultimately leading to lactate accumulation and tumor angiogenesis." (PMID 41184227, 2025). "Surprisingly, the antitumor capacity in terms of tumor growth and NK cell infiltration was lost in NLS-C123A group, indicating that the function of nuclear ACAT1 still requires its enzymatic activity." (PMID 40289129, 2025). "Cholesterol esterification, mediated by ACAT1 and ACAT2, is essential for converting free cholesterol into cholesteryl esters, promoting lipid droplet formation and supporting tumor survival in cholesterol-rich environments." (PMID 40370434, 2025). "Subsequent in vitro and in vivo experiments demonstrated that ACAT1 knockdown impeded BLCA cell migration and proliferation, resulting in diminished distant lung metastasis and tumor growth." (PMID 38817856, 2024). "The MREs ACAT1, ACAT2, FDFT1, FDPS, HMGCL and PMVK were highly expressed in basal tumor cells and urothelial cells." (PMID 39521858, 2024). "Moreover, increased ACAT1 mRNA expression was observed in BLCA patients with high-grade disease, high-T stage disease, or muscle invasion, suggesting that ACAT1 mRNA expression level was positively correlated with tumor grade and T stage and that ACAT1 may promote muscle invasion." (PMID 38817856, 2024). "In summary, our study reveals that ACAT1 was up-regulated in BLCA and was positively related to tumor grade." (PMID 38169575, 2024). "We observed that ACAT1 was significantly up-regulated in BLCA and positively correlated with tumor grade." (PMID 38169575, 2024). "To further investigate this possibility, we overexpressed ACAT1 in MKN45 cells and examined its effect on the expression of tumor stem cell markers." (PMID 39247186, 2024). "CD19-CAR T cells with ACAT1 interference led to better treatment results compared with conventional CD19-CAR T cells, the tumor was undetectable and the survival rate was highest in the shACAT1-19CAR T group." (PMID 38534399, 2024). "We elucidated the role of the ACAT1-FAO-PC pathway in controlling the differentiation and growth of tumor cells." (PMID 39494339, 2024). "In tumor samples from 10 HCC patients, PMVK, GAD1, and ACAT1 were significantly upregulated relative to matched normal liver tissues." (PMID 39325640, 2024). "Acetyl-CoA acetyltransferase 1 (ACAT1) has been shown to be downregulated in KIRC and overexpression of ACAT1 can inhibit the secretion of MMP7 in KIRC cells, thereby inhibiting tumor invasion." (PMID 37627013, 2023). "This further verified that NAMPT and ACAT1 play biological roles mainly by regulating the energy metabolism of various cell types, whereas IDO1 affects tumor progression by regulating the activity of immune cells." (PMID 37954600, 2023). "As for the ACAT1 and CYP2C9, overexpression inhibits the proliferation and migration of tumor cells." (PMID 36632140, 2023). "The enzyme ACAT1, just downstream of SCOT, forms active stable tetramers in tumor cells (tyrosine 407 phosphorylation); this triggers the SCOT reaction and the synthesis of acetyl-CoA through ketolysis." (PMID 36836124, 2023).
tumor (continued). "Y407 phosphorylation of the ACAT1-tetramer by epidermis growth factor (EGF) stabilizes the active ACAT1-tetramer and supports cancer cell proliferation and tumor growth." (PMID 37958351, 2023). "Pharmacologic inhibition in tumor cells and CD8+ T cells of acyl-CoA cholesterol acyltransferase 1 (ACAT1), which promotes cholesterol esterification, inhibits cancer cell growth." (PMID 37842241, 2023). "In this study, the expression of ACAT1 was analysed by immunohistochemistry (IHC) in 61 OSCC patients and compared between OSCC and adjacent pre-tumour tissue of 21 patients." (PMID 36816175, 2023). "In tumor cells, ketolysis “via” succinyl-CoA: 3-oxoacid-CoAtransferase (SCOT) and acetyl-CoA acetyltransferase 1 (ACAT1) is a major source of mitochondrial acetyl-CoA." (PMID 36836124, 2023). "As a result, ACAT1, ADH4 and ECI1 were even more down-regulated in HBV-positive HCC tumor tissue, and ACAT1, ADH4 and ACSL3 were down-regulated in HepG2.2.15 to a higher degree." (PMID 37957550, 2023). "In the current study, we investigated the ACAT1 protein expression by IHC in a series of 61 OSCC patients and compared the results between OSCC and adjacent pre-tumour tissues." (PMID 36816175, 2023). "Our study highlights differences in protein expression levels of ACAT1 between OSCC patients, as well as between OSCC and adjacent pre-tumour tissues." (PMID 36816175, 2023). "We detected seven pairs of ccRCC tissues and corresponding para-carcinoma tissues and found a significantly lower level of ACADM and ACAT1 mRNA and a higher level of CPT1B and HACD1 mRNA in tumor tissues." (PMID 35873479, 2022). "Therefore, ACAT1-deficient CD8+T cells have been shown to enhance the function and proliferation of effector cells by accelerating immune synapse formation and improving TCR aggregation and signal transduction to increase the damage to tumor cells and improve the therapeutic effect of GC." (PMID 35444235, 2022). "Membranous immunoreactivity of SR-B1 (p = 0.0289), and cytoplasmic immunoreactivity of ACAT1 (p = 0.0004), ACAT2 (p < 0.0001), HSL (p < 0.0001) and DHCR24 (p < 0.0001) were significantly higher in compact than in clear tumor cells." (PMID 35216289, 2022). "Indeed, a significant correlation was observed between peritoneal fluid and tissue ACAT1 and CE levels; therefore, peritoneal fluid levels may predict the local tumor status and may serve as potential surrogate markers for diagnosis and aggressiveness in EOC patients." (PMID 35399074, 2022). "Some studies have also shown that silencing ACAT1 or using ACAT1 inhibitors such as ATR-101, avasimibe can effectively inhibit tumor cell growth." (PMID 34604067, 2021). "In this study, we show that the enzyme ACAT1, catalyzing the first step of ketogenesis, is inactivated in NPC cell lines and primary tumor tissues." (PMID 34485115, 2021). "ACAT1 exhibits acetyltransferase activity and can acetylate pyruvate dehydrogenase (PDH), which affects tumor growth." (PMID 33402113, 2021). "The analysis showed that the expression of ACAT1, BDH1 and SLC16A1 was significantly higher in bone metastatic samples when compared with the primary tumor site (P = 0.0042, P = 0.0091, and P = 0.0006, respectively)." (PMID 34584218, 2021). "To confirm the tumor promoting capacity of ACAT-1, we inhibited ACAT-1 expression and activity by treating our cell lines with an ACAT inhibitor, avasimibe, or by stable transfection with ACAT-1 specific short hairpin RNA (shRNA)." (PMID 31978092, 2020). "Another report shows that the treatment of triple negative breast cancer cells with bitter melon extract reduces the accumulation of esterified cholesterol, ACAT1, and LDL receptor expression, thereby reducing tumor growth in mammospheres implanted into mice." (PMID 32458269, 2020). "Yang and others proposed to use avasimibe, an inhibitor of the cholesterol esterification enzyme ACAT1/SOAT1, for therapy to improve CD8+ T cell mediated control of tumor growth." (PMID 31681760, 2019).
tumor (continued). "A Random Forest Classifier model showed that, in eight of the nine tumor cohorts, these patterns were largely determined by a small subset of transcripts, comprised of DHCR24, HMGCS2, PMVK and ACAT1/2." (PMID 31242205, 2019). "3-Oxoacid CoA-transferase 1 (OXAT1) and acetyl-CoA acetyltransferase 1 (ACAT1) are proteins localized in mitochondria and are involved in utilization of ketone bodies to aid in tumor growth and metastasis." (PMID 30410721, 2018). "In glioblastoma, inhibition of ACAT1 increased cholesterol levels, leading to inhibition of SREBP-1 and suppression of lipogenesis and tumour growth." (PMID 30081476, 2018). "In early stage of tumor tissues or normal tissues, where the microenvironment is still subjected to immune surveillance, cytokines secreted by immunocytes, such as IL18 and IL12, can stimulate nuclear translocation of ACAT1 to strengthen antitumor immunity." (PMID 40289129, 2025). "Consequently, TRIM8-mediated PGK1 K63 ubiquitination and ACAT1-dependent PGK1 acetylation are required for glycolysis, which promotes lactate accumulation and tumor angiogenesis." (PMID 41184227, 2025). "Importantly, depleting B cells with an anti-CD20 antibody or inhibiting TLS formation with TAK-799 (also known as TAK-779), an inhibitor of CCR5 and CXCL13/CXCR5, abolished Acat1 knockdown–induced TLS formation and tumor control." (PMID 40166937, 2025). "Interestingly, ACAT1 inhibition also enhances the cytotoxic function of CD8(+) T cells, suggesting a potential immunomodulatory role in controlling tumor growth." (PMID 40370434, 2025). "Strikingly, Acat1 suppressed tumor growth in immunocompetent mice but not in immunodeficient mice; additionally, cells whose expression level of rAcat1 was close to wild type cells grew at the same rate of wild type cells." (PMID 40289129, 2025). "When HA-mp50 WT expressing, Acat1 S58D significantly restrained tumor growth compared to Acat1 WT; however, when HA-mp50 K144R expressing, Acat1 S58D failed to inhibit tumor growth." (PMID 40289129, 2025). "The glycolytic genes, HK2, GAPDH and ENO1, were chosen as they mediate early, mid and final stages of glycolysis respectively, and all three ketolytic genes BDH1, OXCT1 and ACAT1 were analysed for MYCN amplification, survivability and tumour stage progression in three NB datasets." (PMID 41420301, 2025). "Notably, a low level of ACAT1 pS60 corresponds to a low abundance of NK cells in CRC tumor tissues and unfavorable outcomes in patients with CRC, indicating the prognostic value of ACAT1 pS60." (PMID 40289129, 2025). "Among all previous enzymes mentioned, it has been reported that tumours exhibit high expression of ACAT1, one of the isoforms of ACAT, accompanied by elevated levels of CEs, indicating that ACAT1 is crucial for cancer cells to regulate cholesterol metabolic homeostasis." (PMID 40723223, 2025). "ACAT1 overexpression enhanced tumor growth in HCC xenografts and GNPAT deletion could attenuate ACAT1-induced HCC growth, and ACAT1 overexpression with GNPAT inhibition diminish fatty acid synthesis and lipogenesis." (PMID 38720812, 2024). "Precisely, ACAT1-mediated GNPAT acetylation could inhibit GNPAT degradation by repressing TRIM21-mediated GNPAT ubiquitination, ultimately promoting tumor growth in HCC xenografts." (PMID 38720812, 2024). "In comparison to ACAT1, it was affirmed that ACSL3 in tumor tissues was up‐regulated." (PMID 39323079, 2024). "This is achieved by recruiting and activating GAD1 and ACAT1, leading to GABA accumulation, increased efficiency of 4‐Ac‐GABA synthesis, and the suppression of CD8+ T cell activation, intratumoral infiltration, and anti‐tumor responses." (PMID 39325640, 2024). "Due to the inhibitory effect of ACAT1 on PDC by acetylating PDH and PDH phosphatase, AH treatment could enhance PDC flux and oxidative phosphorylation to impair tumor growth, making ACAT1 a potential anti-tumor target." (PMID 38720812, 2024).
tumor (continued). "In support of these observations, the literature data shows that HER2-amplified cell lines and tumor samples both have elevated FASN and ACAT1 function (fatty acid synthesis), leading to poor prognosis and inhibitors to such targets enhance the efficacy of anti-HER2 therapies." (PMID 37414767, 2023). "Comparison of ACAT1 expression, one of the key enzymes in the ketone body metabolic pathway, divided OSCC patients into two groups: 1) similar expression and 2) different expression of ACAT1 in tumour and adjacent pre-tumour tissue." (PMID 36816175, 2023). "The anti-tumor actions of ACOX1, ACAT1, ACADVL, and ACADM were identified as prospective targets." (PMID 37538114, 2023). "Specifically, reduced ACAT1‐catalysed CE synthesis leads to free cholesterol accumulation, decreased LDL receptor levels and reduced essential fatty acid uptake, thereby impairing cell proliferation and tumour growth in vivo." (PMID 36852470, 2023). "Previous studies have shown that mutant ACAT1 can deacetylate PDH and inhibit tumor proliferation." (PMID 37375824, 2023). "Furthermore, blockage of ATM, MAPK, and mTOR signaling pathways with inhibitors also prevented citrate‐induced overexpression of ACAT1/2 and cPLA2α for LD formation in MCF7 and HCT116 tumor cells." (PMID 34747157, 2022). "In addition, ACAT1 and ACAT2 were both significantly higher in compact than clear tumor cells, suggesting that they were in equilibrium with cholesterol ester metabolism to maintain the homeostasis of intracellular free cholesterol levels." (PMID 35216289, 2022). "The molecular mechanism linking ACAT1 mediated inhibition of CE accumulation to tumor suppression is still not clear." (PMID 35399074, 2022). "Elevation of cholesterol levels by blocking cholesterol esterification with ACAT1/2 inhibitors facilitates the direct movement of TCR microclusters to the synapse center, accompanied by elevated numbers and anti-tumor activity of CD8+ T cells both in vitro and in vivo." (PMID 34742349, 2021). "In contrast, ACAT1 knockdown boosted rather than constrained the anti-tumour potential of T cells in murine melanoma models." (PMID 33990561, 2021). "Further validation via another database revealed that 4 hub genes, ACAT1, SLC2A2, PCK1 and ABAT, were correlated with tumor survival of HCC in T2DM with HbA1c ≥ 6.5%, suggesting the prognostic prediction function of these 4 genes and even new therapeutic targets in HCC." (PMID 33865459, 2021). "This loss of co-expression suggests that the flux generated by these pathways is no longer coupled to the flux through ACAT1 in tumor cells." (PMID 25961905, 2015). "Consequently, bioluminescence images and hematoxylin and eosin (H&E) staining of tumor tissues indicated that despite the identical mitochondrial level of ACAT1 in the WT and NES groups, the antitumor capacity was deprived in NES group; moreover, tumor growth was impaired in NLS group." (PMID 40289129, 2025). "To further confirm that p50 K146ac contributed to the antitumor immune function of ACAT1 pS60, we induced Acat1-Flag WT or S58D expression in Nfkb1-depleted CT26 cells rescued with HA-mp50 (1-364aa) WT or K144R (equivalent to K146R in humans) and performed subcutaneous tumor model." (PMID 40289129, 2025). "It was noted that the mitochondrial levels of Acat1-Flag NLS-C123A and Acat1-Flag NLS were identical, but the antitumor effects of these two mutants were clearly different, also reflecting that nuclear but not mitochondrial ACAT1 facilitates cytotoxic NK cell recruitment and impairs tumor growth." (PMID 40289129, 2025). "Furthermore, since these pathological samples were obtained from surgeries at the initial stages of cancer, accurately assessing the discrepancy in ACAT1 expression levels between BLCA tissues and paired adjacent tissues during tumor metastasis has become challenging." (PMID 38817856, 2024).
tumor (continued). "Additionally, the ACAT1 expression in cancerous tissues compared to adjacent pre-tumour tissues did not follow any specific trends in all the patients." (PMID 36816175, 2023). "In addition, the increased level of cholesterols regulated by cholesterol acyltransferase 1 (ACAT1) could enhance CD8+ T cell proliferation and support anti-tumor immunotherapy." (PMID 37858219, 2023). "The cholesterol esterification enzyme acetyl-CoA acetyltransferase (ACAT1) knockout in CD8+ T cells was found to downregulate membrane cholesterol and improve T cell receptor clustering and signaling, enhancing CD8+ T cell function and anti-tumor immunity in mouse tumor models." (PMID 37210507, 2023). "Although considerable research has been carried out with tumor tissues to establish ACAT1 as a potential new prognostic marker in these cancers, there have been very few studies examining ACAT1 expression and CE levels in tissue and plasma, and none within peritoneal fluid of EOC patients." (PMID 35399074, 2022). "Therefore, this study was the first proposed the relationship between ABCB6, IPO7, TIMM9, and ACAT1 and HBV, and they may be related to tumor progression in HBV-induced HCC as FZD7." (PMID 36685852, 2022). "Since KB appeared as the main route fueling energy during relapse to ADT, inhibition of ACAT1 may block this energy source rather than trigger lactate production in this type of tumor." (PMID 34584218, 2021). "Along with these results, the proportions of tumor-infiltrating cytotoxic NK cells were boosted up by S58D expression in mp50 WT group, but declined in both of the HA-mp50 K144R groups, regardless of whether Acat1 WT or S58D was expressed." (PMID 40289129, 2025). "In our study, metabolomics analysis revealed that the knockdown of ACAT1 could activate the thiamine metabolic pathway, which is attributed to the upregulation of TPK1 expression, and further restore the activity of PDH and the function of OXPHOS in tumor cells." (PMID 37375824, 2023). "This could lead to overinterpretation of the role of genes like ACAT1 and ACSL3 without understanding the precise mechanisms by which they influence tumor behavior." (PMID 39323079, 2024). "However, the downregulation of ASNS, ACAT1, and GNMT expression had no significant impact on tumor invasion." (PMID 37511510, 2023).